SUCLG2P2 (SUCLG2 pseudogene 2)
Gene: Processed pseudogene on chromosome 12 (94,548,241 to 94,549,536, forward strand). Ensembl gene ENSG00000236349.
Diseases named in the same sentence as SUCLG2P2 in open-access papers:
SUCLG2P2 is named in the same sentence as 3 diseases in open-access papers, as found by Europe PMC text mining. Sharing a sentence is not in itself a finding about the gene and the disease. The quoted sentences say what the papers report.
colon cancer (2 papers, 2021 to 2025). "Combined with our experimental results, the low expression of SUCLG2P2 in many tumors, especially low expression in colon cancer, could be used as a diagnostic marker." (PMID 34589110, 2021). "SUCLG2P2 downregulation alongside SUCLG2 in colon cancer implies a shared mechanism in carcinogenesis." (PMID 40556338, 2025). "The expression of SUCLG2P2 was also low in colon cancer, but the expression of ATIC was high in most tumors, including colon cancer." (PMID 34589110, 2021). "SUCLG2P2 is highly homologous with SUCLG2, and is associated with colon cancer stage, metastasis and survival." (PMID 34589110, 2021). "When the expression of SUCLG2P2 decreases in colon cancer, the combined hsa-miR-588 decreases, which increases the binding of hsa-miR-588 to SUCLG2, which in turn leads to an increase in SUCLG2 degradation and a decrease in SUCLG2 expression." (PMID 34589110, 2021). "Association between SUCLG2P2, SUCLG2 and ATIC genes and clinicopathological parameters of colon cancer patients." (PMID 34589110, 2021). "The pseudogene SUCLG2P2 along with two other genes (SUCLG2 and ATIC) were introduced as potential prognostic markers for colon cancer, aiding in predicting patient outcomes and tailoring treatment strategies." (PMID 40556338, 2025). "In conclusion, the expressions of SUCLG2P2, SUCLG2 and ATIC in colon cancer and normal tissues were different, and they were related to survival." (PMID 34589110, 2021). "In colon cancer, the expressions of SUCLG2 and SUCLG2P2 are reduced, the competitive binding hsa-miR-588 is reduced, hsa-miR-588 is increased, and hsa-miR-588 exerts a tumor suppressor effect." (PMID 34589110, 2021).
tumor (1 paper, 2021). "We considered the combination of SUCLG2 and SUCLG2P2 with common miRNA to achieve consistent expression and exert a tumor suppressor effect to affect the prognosis of patients." (PMID 34589110, 2021). "In our study, clinicopathological parameter sage, tumor stage, lymphatic, hematogenous metastases and SUCLG2, SUCLG1, ACLY, SUCLG2P2, ATIC and ACO2 genes were found to be associated with survival in univariable or multivariate analysis." (PMID 34589110, 2021). "Pearson analysis showed that SUCLG2P2, SUCLG2 and ATIC were correlated in normal COAD tissues, while only SUCLG2P2 and SUCLG2 were correlated in tumor tissues." (PMID 34589110, 2021). "The results showed that the three variables SUCLG2P2, ACO2 genes and clinicopathological parameter stage were different between the normal group and the tumor group." (PMID 34589110, 2021). "Analyzing the downloaded TCGA data showed that the expression of ATIC was up-regulated in the tumor, and that of SUCLG2P2 was consistent with that of SUCLG2, the mRNA expression of SUCLG2P2 and SUCLG2 were down-regulated in the tumor." (PMID 34589110, 2021). "We also confirmed the expression levels of SUCLG2P2, SUCLG2 and ATIC mRNA in tumor and non-tumor tissues from 10 patients with CRC." (PMID 34589110, 2021).
SUCLG2P2 also shares sentences with these, for which no sentence is quoted: cancer (1 paper).